BCL11B (BCL11 transcription factor B)
Diseases named in the same sentence as BCL11B in open-access papers (continued):
Sharing a sentence is not in itself a finding about the gene and the disease.
B-cell chronic lymphocytic leukemia (9 papers, 2010 to 2024). "BCL11B is a hallmark of B-cell Chronic Lymphocytic Leukemia (CLL)." (PMID 38466776, 2024). "Among the targets, 8 genes (including 3 up-regulated genes and 5 down-regulated genes; such as B-cell CLL/lymphoma 11B, BCL11B) were differentially expressed in this study." (PMID 30497506, 2018). "The B-cell chronic lymphocytic leukemia (CLL)/lymphoma 11B (BCL11B) gene was first identified on human chromosome 14q32.2 and encodes a Krüppel-like C2H2 zinc finger protein initially identified as a transcriptional repressor." (PMID 21575156, 2011). "The B-cell chronic lymphocytic leukemia (CLL)/lymphoma 11B (BCL11B) gene plays a crucial role in T-cell development, differentiation, and proliferation, and altered expression, mutation, disruption, or rearrangement of BCL11B have been associated with T-cell malignancies." (PMID 21080944, 2010). "Moreover, miRNA-125b-1-3p in EVs was highly expressed in human adipose-derived MSCs and reduced B-cell chronic lymphocytic leukemia (CLL)/lymphoma 11B (BCL11B) levels in lymphocyte, leading to lymphocyte apoptosis in atherosclerotic arterial tissues and in amelioration of atherosclerosis." (PMID 34692785, 2021). "Based on a genome-wide analysis of aberrant DNA methylation in chronic lymphocytic leukemia (CLL) using methylated CpG island amplification (MCA), coupled with a promoter microarray, methylation status was confirmed through pyro-sequencing for 22 of these genes in 78 CLL patients, including BCL11B." (PMID 23211040, 2012).
Intellectual disability (9 papers, 2018 to 2025). "Recent reports have described 11 monoallelic variants at the BCL11B locus that were linked to craniofacial dysmorphisms, neurodevelopmental pathologies, intellectual disabilities, dental anomalies and dermal defects." (PMID 31067316, 2019). "Coherently, mutations in POU3F3, SATB2, BCL11B, or TBR1 are associated with NDDs, including intellectual disability (ID) and autism spectrum disorder (ASD)." (PMID 39878593, 2025).
schizophrenia (9 papers, 2017 to 2024). A major psychotic disorder characterized by abnormalities in the perception or expression of reality. "Furthermore, several studies have recently demonstrated genome-wide significant enrichment of polymorphisms increasing risk for schizophrenia (SCZ) in the BCL11B gene." (PMID 37519464, 2023). "Interacting partners BCL11B and GATAD2A are also schizophrenia risk genes indicating that other genes interacting with or are regulated by SATB2 are making a contribution to schizophrenia and cognition." (PMID 30040823, 2018).
T-cell leukemia (9 papers, 2010 to 2024). A malignant disease of the T-lymphocytes in the bone marrow, thymus, and/or blood. "In contrast, mouse models of T-cell leukemia revealed frequent homozygous deletions or mutations within the BCL11B locus." (PMID 20824091, 2010). "The fusion gene STIL-TAL1 and mutations in BCL11B, NOTCH1, and USP7 have been associated with T-cell leukemia." (PMID 38363891, 2024). "The fusion gene STIL-TAL1 and mutations in BCL11B, NOTCH1, and USP7 have also been found and all been associated with the occurrence of T-cell leukemia." (PMID 38363891, 2024). "For example, in an adult T cell leukemia patient, the 5′ region of the BCL11B gene was found fused to intron 3 of the HELIOS gene, which interestingly, we also identified as HDAC1 interaction." (PMID 23752268, 2013). "We developed a retrovirus-mediated BCL11B overexpression system in two different T cell leukemia cell lines and focused our research on apoptosis and proliferation." (PMID 20824091, 2010). "This resulted in an over 20-fold upregulation of BCL11B mRNA expression which reached (huT78) or exceeded (Jurkat) the average expression level measured in primary T-cell leukemia samples." (PMID 20824091, 2010). "Two different T-cell lines were forced to express BCL11B at levels similar to those observed in primary T-cell leukemias." (PMID 20824091, 2010).
neuroblastoma (8 papers, 2010 to 2025). Neuroblastoma (NB) is the most common solid, extracranial childhood tumor. "For example, BCL11B has been implicated in cell cycle progression by directly repressing the cell cycle inhibitors p21WAF1 and p57KIP2 in microglial cells and SK-N-MC (which were originally characterized as a neuroblastoma cell line, but are in fact a Ewing cell line) cells, respectively." (PMID 23527175, 2013). "BCL11B, which was previously shown by microarrays and rt-PCR to be downregulated in PD blood was also downregulated in rotenone-treated neuroblastomas, and so was the creatine neurotransmitter transporter SLC6A8." (PMID 20161708, 2010). "In the current study, we confirmed the high specificity of BCL11B and GLG1 for EwS in a far larger and independent cohort of 133 EwS and 320 non-EwS from 11 differential diagnoses, including 118 samples from close morphological mimics such as DSRCT, neuroblastoma, and rhabdomyosarcoma." (PMID 32164354, 2020).
acute leukemia (7 papers, 2015 to 2025). A clonal (malignant) hematopoietic disorder with an acute onset, affecting the bone marrow and the peripheral blood. "Recently, a study on acute leukemias of ambiguous lineage showed the recurrence of 14q32 rearrangements resulting in the activation of BCL11B, co-occurring with FLT3, DNMT3A, TET2 and WT1 variants." (PMID 34930475, 2021). "GEP identified a specific expression signature related to BCL11B activation with significant downregulation of its targets, providing a novel biomarker for a new entity among immature acute leukemias." (PMID 34930475, 2021). "BCL11B rearrangements define a heterogeneous group of acute leukemias that may present as AML, mixed phenotype acute leukemia (MPAL), T/myeloid, or T-LL." (PMID 41374977, 2025). "BCL11B rearrangements are found in T-ALL, MPAL and immature AML, advocating the introduction of BCL11B FISH probes into routine diagnostics for classification of acute leukemia’s of ambiguous lineage according to the 5th edition of the WHO classification." (PMID 36335263, 2023).
acute myeloid leukemia (7 papers, 2012 to 2024). Acute myeloid leukemia (AML) is a group of neoplasms arising from precursor cells committed to the myeloid cell-line differentiation. "In humans, chromosomal translocations involving the BCL11b gene locus were identified in patients with acute myeloid leukemia (AML), T-ALL and T/myeloid acute bilineage leukemia." (PMID 25023966, 2014). "Interestingly, chromosomal rearrangements involving BCL11B, have also been found in acute myeloid leukemia (AML)." (PMID 38472338, 2024).
thymic lymphomas (6 papers, 2009 to 2024). "This gene was originally referred to as RIT1 (radiation-induced tumor suppressor gene 1) because BCL11B was isolated by scanning γ-ray-induced mouse thymic lymphomas for the loss of specific chromosomal DNA." (PMID 23211040, 2012). "Moreover in a mouse model of thymic lymphoma, spontaneous homozygous deletions and point mutations occurred in Bcl11b." (PMID 23527175, 2013).
Alzheimer disease (5 papers, 2017 to 2025). A progressive, neurodegenerative disease characterized by loss of function and death of nerve cells in several areas of the brain leading to loss of cognitive function such as memory and language. "A recent genome wide association study of 41 families with hereditary late onset Alzheimer's disease (LOAD) identified Bcl11b as a novel gene defect involved." (PMID 28424591, 2017).
asthma (5 papers, 2012 to 2024). "While we report the first case of EoE with BCL11B mutation, associations between BCL11B gene mutation and other atopic diseases, such as severe asthma and allergies, have been previously reported." (PMID 39610427, 2024). "We identified major defects in the capacity of Bcl11b-deficient T-helper cells to differentiate into Th2 cells in vivo, causing diminished responses to helminth infection and reduced severity of asthma." (PMID 29700302, 2018). "Here the authors show that Bcl11b is required to license the Th2 program of helper T cell differentiation and restrict alternate lineage gene expression using in vivo models of helminth infection and asthma." (PMID 29700302, 2018). "We focused on genes related to Th2 response, and found that the Rad50 HS 5 (RHS V) within the Th2 cytokine LCR had significantly reduced accessibility in Bcl11b-deficient T-helper cells compared to WT cells from asthma-induced mice, despite the fact that Bcl11b did not bind to this region." (PMID 29700302, 2018).
atopic dermatitis (5 papers, 2009 to 2023). "We present a 6-year-old male patient with markedly elevated IgE and severe atopic dermatitis presenting with staphylococcal bacteremia found to have a heterozygous variant in FLG (p.S3247X) and multiple variants of unknown significance in BCL11B, ZAP70, LYST, and PTPRC." (PMID 34603803, 2021).
breast carcinoma (5 papers, 2009 to 2025). "Cai and colleagues reported that Bcl11b regulates the mammary epithelial stem cell quiescence, binds to the promoters of Wnt target genes and inhibits Wnt signaling in breast cancer." (PMID 39433900, 2024). "Exploring whether pathways regulated by Mycn in mammary development are abnormally activated in breast cancer, as well as the expression correlation of Mycn, Bcl11b, and Tspan8 in human breast cancer samples, will be of significant value." (PMID 40862719, 2025).
allergic asthma (4 papers, 2018 to 2023). A asthma with a basis in a pathological type I hypersensitivity reaction. "Taken together, these results demonstrate that the removal of Bcl11b from mature T-cells results in reduced pulmonary pathology after induction of allergic asthma, which was associated with reduced lung eosinophils and CD4+ T-cells." (PMID 29700302, 2018). "In an allergic asthma model, IRF7 mediated the activation and function of ILC2s cells through BCL11B, increasing the expression of IL-5 and IL-13, which in turn promoted allergic respiratory inflammation and allergic asthma." (PMID 37251373, 2023). "Here we report that mice lacking Bcl11b in mature T-cells have a diminished capacity to mount Th2 responses during helminth infection and allergic asthma, showing reduced Th2 cytokines and Gata3, and elevated Runx3." (PMID 29700302, 2018).
allergies (4 papers, 2021 to 2025). "It is possible that the p.Cys826Tyr BCL11B variant alters the binding affinity of WT BCL11B to its targets or causes protein complexes to bind to new targets, leading to a predisposition to developing allergic disease." (PMID 34887873, 2021). "Furthermore, in IgE-mediated cow’s milk allergy, we observed that genes such as TCF7, EVL, and BCL11B could be associated with allergy remission and tolerant responses, making them potential candidates as biomarkers for CMA and its prognosis regarding recovery." (PMID 41394805, 2025). "Notable genes associated with allergy, immune responses, and inflammation were found (LCK, BACH2, SATB1, LIME1, KSR1, BCL11B, TCF1, and EVL)." (PMID 41394805, 2025). "Our patient with BCL11B frameshift variants had no history of allergies or infections." (PMID 36683525, 2023).
colorectal cancer (4 papers, 2020 to 2024). A primary or metastatic malignant neoplasm that affects the colon or rectum. "Collectively, these data suggest that intestinal epithelial Bcl11b expression is correlated with colorectal cancer." (PMID 39433900, 2024). "Our findings are in line with previous studies of colorectal cancers and clearly identify BCL11B as an inhibitor of CSC traits in HCC22,31." (PMID 33093445, 2020). "CB1 signal, in presence of THC, promotes the activity of the transcription factor B-cell lymphoma/leukemia 11B (BCL11B), which in turn generate neurons expressing transmembrane protein deleted in colorectal cancer (Dcc) and reduced level of UNC-5 netrin receptor C (Unc5C)." (PMID 34684894, 2021). "Furthermore, Bcl11b deletion prevents proliferation and tumorigenesis of colorectal cancer cells." (PMID 39433900, 2024). "Since Lgr5+ stem cells play important roles in colorectal cancer (CRC) development, we examined the role of Bcl11b in this process." (PMID 39433900, 2024). "Elevated expression levels of PAX6, BCL11B, MCOLN2, CUX1 and EMX1 reported in colorectal cancer positively correlate with TRPA1 in other malignancies, with a possible implication in tumorigenesis." (PMID 39770499, 2024).
head and neck squamous cell carcinoma (4 papers, 2009 to 2021). A squamous cell carcinoma that arises from any of the following anatomic sites: lip and oral cavity, nasal cavity, paranasal sinuses, pharynx, larynx, and salivary glands. "The induction of BCL11B expression correlates with reduced differentiation status in head and neck squamous cell carcinomas." (PMID 23383087, 2013). "Furthermore, BCL11B induction correlated with the low differentiation status in head and neck squamous cell carcinoma where Bcl11b co-localized with the cancer stem cell marker BMI-1." (PMID 20824091, 2010). "However, the majority of T-ALL and other malignancies originating from BCL11B-positive tissues, such as head and neck squamous cell carcinomas (HNSCC), Ewing sarcomas or neuroblastomas (NBs) are characterized by elevated expression of non-altered gene (, unpublished observation)." (PMID 33807484, 2021).
sarcoma (4 papers, 2013 to 2023). A usually aggressive malignant neoplasm of the soft tissue or bone. "Only those smaller and rounded cells showed co-localization of both FISH and Bcl11b, indicating that HAdV DNA is specifically found in the infiltrated T-lymphocytes inside sarcoma tissue samples." (PMID 23671688, 2013). "While 88% of tested Ewing-like sarcomas displayed strong CD99-immunoreactivity, none displayed combined strong BCL11B- and GLG1-immunoreactivity." (PMID 29416716, 2018). "Interestingly, the tested series of PDX models included five samples from so-called ‘Ewing-like’ sarcomas (3 CIC-DUX4-positive sarcomas and 2 BCOR-rearranged sarcomas), which did not exhibit any BCL11B and GLG1 immunoreactivity." (PMID 32164354, 2020).
Sepsis (4 papers, 2018 to 2025). Sepsis is defined as life-threatening organ dysfunction caused by a dysregulated host response to infection. "Sequencing analysis of mouse peripheral blood demonstrated that BCL11B decreased in sepsis compared to the control group." (PMID 36918563, 2023). "The present study found that BCL11B was correlated with a favorable sepsis prognosis and was mainly located in T cells." (PMID 36918563, 2023). "Further analysis of the correlation between sepsis feature genes and immune cells revealed that CLU, GLPX, and CKAP4 were negatively correlated with CD4 naive T cells, while DPEP2 and BCL11B were positively correlated." (PMID 41359645, 2025). "The expression results of core genes in different samples showed that five genes (BCL9L, BCL11B, CD96, SAMD3 and CD247) were decreased in sepsis samples, compared with the normal group." (PMID 36918563, 2023). "BCL9L, BCL11B, CD247, CD96 and SAMD3 were decreased in sepsis and mainly expressed in the T cell; while MAFG increased in sepsis and localizes to monocytes." (PMID 36918563, 2023). "Ultimately, by taking the intersection of the results from the three machine learning methods, we identified six feature genes in sepsis: CD81, CLU, GLRX, CKAP4, DPEP2, and BCL11B; and seven feature genes in atrial fibrillation: LDHB, CD81, PFKFB2, CKAP4, CXCR4, DPEP2, and RORA." (PMID 41359645, 2025). "Moreover, CEBPB and has-miR-150 might function in neonatal sepsis separately through targeting MAPK14 and BCL11B in the regulatory networks." (PMID 30497506, 2018).
Stroke (4 papers, 2019 to 2024). Sudden impairment of blood flow to a part of the brain due to occlusion or rupture of an artery to the brain. "BCL11B and SATB2 appear as potential molecular markers for predicting better outcomes of the stroke recovery as well as potential targets for therapeutical interventions after ischemic stroke." (PMID 37237015, 2023). "This allowed to correlate the expression of BCL11B or SATB2 to the structural and functional outcomes, indicating their potential involvement into post-stroke events." (PMID 37237015, 2023). "Therefore, the results suggested that BCL11B and ATF3 might have synergistic effect promoting functional recovery after stroke." (PMID 37237015, 2023). "We could not test direct involvement of both BCL11B and SATB2 in the recovery after stroke, as respective mutant mice do not survive after birth and show a plethora of defects, including brain malformations." (PMID 37237015, 2023).
T cell lymphomas (4 papers, 2009 to 2018). "Evidence for aberrant V(D)J rearrangements in 73-deficient thymocytes was obtained by assaying for internal deletion at the Bcl11b and Notch1 loci, which both contain cryptic recombination signal sequences (RSS) that are accessible to Rag, and are frequently mutated in T cell lymphomas." (PMID 19907659, 2009).
autism spectrum disorder (3 papers, 2018 to 2025). A spectrum of developmental disorders that includes autism, and Asperger syndrome. "A number of neurodegenerative and neurodevelopmental diseases, e.g., Alzheimer’s and autism spectrum disorder, are associated with a decrease in synaptic density suggesting that loss of Bcl11b/Ctip2 could contribute to these neurological disorders." (PMID 29674952, 2018).
glioma (3 papers, 2018 to 2023). A benign or malignant brain and spinal cord tumor that arises from glial cells (astrocytes, oligodendrocytes, ependymal cells). "Based on our previous findings that Bcl11b-KD reduced the expression of stemness-related genes (Sox2 and Bmi1) in glioma cells, we also examined the expression of stemness-related genes in the scramble and Bcl11b-KD cultures." (PMID 29416501, 2018). "Our previous study using human and rat glioma cells also showed that p21 expression was upregulated after the downregulation of Bcl11b expression in glioma cell lines, suggesting that Bcl11b is an important regulator for glioma cell expansion through the repression of p21 action." (PMID 29416501, 2018).